IKZF3 (IKAROS family zinc finger 3)
Description:
Transcription factor that plays an important role in the regulation of lymphocyte differentiation. Plays an essential role in regulation of B-cell differentiation, proliferation and maturation to an effector state. Involved in regulating BCL2 expression and controlling apoptosis in T-cells in an IL2-dependent manner.
Synonyms: ZNFN1A3; Aiolos; AIO; IMD84
Tractability: Small molecule: a high-quality ligand is known. PROTAC: it is named in the literature on targeted protein degradation; UniProt records ubiquitination sites on it; ubiquitination databases record sites on it; its protein half-life has been measured; a small molecule that binds it is known.
Target class: Transcription factor
Chemical probes: Iberdomide
Gene: Protein-coding gene on chromosome 17 (39,757,715 to 39,864,312, reverse strand). Ensembl gene ENSG00000161405.
Subcellular location: Nucleus; Cytoplasm; Nucleus (Isoform 1); Nucleus (Isoform 3); Nucleus (Isoform 11); Nucleus (Isoform 14); Cytoplasm (Isoform 12)
Subcellular location (Human Protein Atlas): Nucleoplasm; Cytosol
Pathways (Reactome):
Chromatin organization: Interaction of NuRD complexes with transcription factors
Gene Ontology:
Molecular function: DNA-binding transcription activator activity, RNA polymerase II-specific; histone deacetylase binding; identical protein binding; promoter-specific chromatin binding; protein binding; protein heterodimerization activity; protein homodimerization activity; sequence-specific DNA binding; DNA-binding transcription factor activity; RNA polymerase II cis-regulatory region sequence-specific DNA binding; DNA binding; RNA polymerase II transcription regulatory region sequence-specific DNA binding
Biological process: regulation of apoptotic process; mesoderm development; regulation of B cell differentiation; regulation of B cell proliferation; regulation of lymphocyte differentiation; regulation of transcription by RNA polymerase II; B cell differentiation; positive regulation of transcription by RNA polymerase II; T cell differentiation
Cellular component: cytoplasm; cytosol; nucleoplasm; nucleus
Genetic constraint (gnomAD): Loss-of-function variants: 4 observed, 37.45 expected, observed/expected ratio (o/e) 0.11, 90% interval 0.052 to 0.24. The upper end of that interval is the gene's LOEUF score, 0.24, which puts it in group 1 of 6, group 1 being the genes least tolerant of losing a copy. Missense variants: 430 observed, 616.91 expected, observed/expected ratio (o/e) 0.7, 90% interval 0.64 to 0.75. Synonymous variants: 190 observed, 214.37 expected, observed/expected ratio (o/e) 0.89, 90% interval 0.79 to 1.
Gene-disease validity (ClinGen):
ClinGen rates the evidence that IKZF3 causes each of these diseases.
immunodeficiency 84 (autosomal dominant): Moderate.
Cancer hallmarks: escaping programmed cell death (suppresses); escaping programmed cell death (promotes); invasion and metastasis (promotes); escaping immune response to cancer; suppression of growth (promotes)
Homologues: Orthologues: chimpanzee IKZF3 (99% identical), macaque IKZF3 (98% identical), rabbit IKZF3 (93% identical), pig IKZF3 (93% identical), dog IKZF3 (91% identical), rat Ikzf3 (88% identical), mouse Ikzf3 (87% identical), guinea pig IKZF3 (86% identical), tropical clawed frog ikzf3 (57% identical), Drosophila melanogaster CG14442 (7% identical), Drosophila melanogaster CG14440 (4% identical). Paralogues in human: IKZF1 (54% identical), IKZF2 (45% identical), IKZF4 (44% identical), ZNF350 (15% identical), ZNF567 (15% identical), ZNF649 (15% identical), ZNF613 (15% identical), ZNF639 (14% identical), ZNF382 (14% identical), ZNF821 (12% identical), ZNF564 (11% identical).
Diseases named in the same sentence as IKZF3 in open-access papers:
IKZF3 is named in the same sentence as 92 diseases in open-access papers, as found by Europe PMC text mining. Sharing a sentence is not in itself a finding about the gene and the disease. The quoted sentences say what the papers report.
multiple myeloma (60 papers, 2014 to 2025). "Degradation of IKZF1 and IKZF3 causesinhibition of the proliferation of multiple myeloma cells and suppressionof the differentiation of B-cells." (PMID 35856839, 2023). "CFT7455, developed by C4 Therapeutics, is a potent degrader of Ikaros (IKZF1) and Aiolos (IKZF3), two transcription factors critical for multiple myeloma cell survival." (PMID 40574056, 2025). "This PROTAC selectively degrades Ikaros (IKZF1) and Aiolos (IKZF3), two essential transcription factors in multiple myeloma cell survival." (PMID 40574056, 2025). "Lenalidomide itself is an analogue of thalidomide, and like thalidomide is known to degrade IKZF1 and IKZF3 in multiple myeloma cells." (PMID 39029626, 2024). "Two zinc finger transcription factors, Ikaros (IKZF1) and Aiolos (IKZF3), which are essential for myeloma cell survival, are recruited to the complex as neo-substrates, resulting in their ubiquitination and subsequent proteasomal degradation." (PMID 36768967, 2023). "For instance, lenalidomide causes selective ubiquitination and degradation of IKZF1 and IKZF3 conferring cytotoxicity in multiple myeloma cells." (PMID 37833543, 2023). "Subsequent ubiquitination and degradation of the transcription factors Ikaros (IKZF1) and Aiolos (IKZF3), which control myeloma survival and proliferation genes (e.g., MYC or IRF4), result in growth limitation and death." (PMID 37744361, 2023). "Lenalidomide, which is approved in the treatment of multiple myeloma, targets IKZF3 for degradation." (PMID 37019979, 2023). "The mechanism of action of lenalidomide includes degradation of the transcription factors Ikaros (IKZF1) and Aiolos (IKZF3), which act as central transcription factors regulating various genes involved in the survival of myeloma cells." (PMID 36094683, 2023). "Utx/BrafV600E plasma cells before and after overt MM showed gradual up-regulation and down-regulation of DEGs, including representative myeloma signature genes with upregulation of Myc, Ccnd2, E2f3, and Irf4 and downregulation of Cd19 and Ikzf3." (PMID 37198323, 2023). "IMiD binding to CRBN resulted in proteasomal depletion of the IKAROS family members IKZF1 (Ikaros) and IKZF3 (Aiolos) that are the lymphoid transcription factors crucial in myeloma cell survival." (PMID 36499765, 2022). "Most important of these are IKZF1 and IKZF3, key MM survival transcription factors which sustain the expression of myeloma oncogenes IRF4 and MYC." (PMID 36439455, 2022). "Recent studies showed that IMiDs bind to cereblon (CRBN), a substrate receptor of the CRL4–CRBN complex, to induce the ubiquitination and degradation of IKZF1 and IKZF3 in MM cells, contributing to their anti-myeloma activity." (PMID 34207079, 2021). "As critical transcription factors for lymphopoiesis and lymphoid malignancies, degradation of IKZF1 and IKZF3 by the CRL4CRBN E3 ubiquitin ligase complex mediates the anti-myeloma effect of lenalidomide." (PMID 34680233, 2021). "Combining a pan-PIM kinase inhibitor with lenalidomide led to more effective degradation of IKZF1 and IKZF3 in multiple myeloma cells as well as xenografts of myeloma tumors." (PMID 34503111, 2021). "In terms of mechanism, treatment with a pan-PIM kinase inhibitor promoted increased ubiquitination and subsequent degradation of IKZF1 and IKZF3, two transcription factors crucial for the survival of myeloma cells." (PMID 34503111, 2021). "IKZF3 is required for the generation of high affinity plasma cells, the physiological counterpart of myeloma cells, during antibody response." (PMID 34680233, 2021). "Rev leads to the proteasomal degradation of IKZF1 and IKZF3, two transcription factors essential for myeloma cell proliferation, whereas this process should be inhibited by Vel." (PMID 34439244, 2021). "IMiDs bind to CRBN and recruit IKZF1 and IKZF3 for their ubiquitination and degradation, leading to the reduced proliferation of myeloma cells." (PMID 33392195, 2020).
multiple myeloma (continued). "In combination with CASP-8 inhibitor, Len further elevates the CRBN protein level, resulting in the enhanced degradation of IKZF1 and IKZF3 and enhanced anti-myeloma activity." (PMID 33392195, 2020). "Recent studies showed that IMiDs bind to CRBN, a substrate receptor of CRL4 E3 ligase, to induce the ubiquitination and degradation of IKZF1 and IKZF3 in multiple myeloma cells, contributing to their anti-myeloma activity." (PMID 31938543, 2020). "IKZF1 and IKZF3 are transcription factors highly expressed in myeloma that contribute to myeloma cell survival." (PMID 30760870, 2019). "Ikaros family zinc finger protein 1 and 3 (IKZF1 and IKZF3) are transcription factors that promote multiple myeloma (MM) proliferation." (PMID 30760870, 2019). "This activation leads to the down-regulation of two transcription factors involved in B cell development (IKZF1 and IKZF3), highly expressed in multiple myeloma." (PMID 30190791, 2018). "They analyzed myeloma cell lines and demonstrated that loss of IKZF1 and IKZF3 is necessary and sufficient for Len’s therapeutic effect." (PMID 29454372, 2018). "The degradation of IKZF1 and IKZF3 induces cytotoxicity in myeloma cells because they are critical factors for B-cell differentiation." (PMID 28894755, 2017). "Recent in vitro studies showed that lenalidomide bound to cereblon and then selectively degraded specific transcription factors — the Ikaros family zinc finger proteins 1 and 3 (IKZF1 and IKZF3) — which were necessary for myeloma survival." (PMID 26447613, 2015). "IKZF1 and IKZF3 zinc finger proteins are essential transcriptionfactors in multiple myeloma." (PMID 35856839, 2023). "IKZF3 is a predictor for survival in multiple myeloma stage III patients." (PMID 34367245, 2021). "Transcription factors IKZF1 and IKZF3 are required for myeloma cells to undergo proliferation." (PMID 33392195, 2020). "IMiD-mediated degradation of IKZF1 and IKZF3 results in myeloma cell growth arrest as well as activation of T cells, both of which may contribute to anti-myeloma effects of IMiDs." (PMID 31231360, 2019). "Indeed, the loss of IKZFs by shRNAs or by expression of a dominant-negative IKZF3 mutant inhibits myeloma growth." (PMID 30760870, 2019). "CC-220 is a significantly more potent IKZF1 and IKZF3 degrader than IMiD drugs, and it is currently in clinical trials for relapsed/refractory multiple myeloma and systemic lupus erythematosus." (PMID 30234487, 2018). "These novel driver mutations hit histone proteins (HIST1H1D; HIST1HIC) involved in resistance to lenalidomide in multiple myeloma (IKZF3), nuclear RNA export factor 1 (NXF1) and proteins also mutated in acute myeloid leukemia and multiple myeloma (ASXL1; TRAF3)." (PMID 27580852, 2016). "Finally, lenalidomide was found to degrade both IKZF1 and IKZF3 in the context of multiple myeloma." (PMID 39029626, 2024). "Furthermore, under physiological conditions, IKZF1 and IKZF3 repress IL-2 gene expression in T cells but conversely stimulate expression of interferon-related factor 4 (IRF4) (a transcription factor essential for survival of myeloma cells)." (PMID 24687382, 2014). "IMiDs are known to induce degradation of zinc-finger transcription factors in myeloma cells, like IKZF1 and IKZF3, and like SALL4 in embryonic stem cells, which is behind their therapeutic, but also teratogenic functions." (PMID 39972349, 2025). "The compound CC-220 is currently in phase III clinical trials for the treatment of systemic lupus erythematosus and relapsed/refractory multiple myeloma, through the induction of IKZF1 and IKZF3 protein degradation." (PMID 40730655, 2025). "The key mechanism of immunomodulators used in myeloma therapy is to promote the ubiquitination of transcription factors IKAROS Family Zinc Finger 1 (IKZF1) and IKAROS Family Zinc Finger 3 (IKZF3) through the action of cereblon, an E3 ligase." (PMID 40259951, 2025).
multiple myeloma (continued). "These compounds serve as molecular glues, redirecting the CRBN E3 ubiquitin ligase to degrade myeloma-dependency factors, IKZF1 and IKZF3." (PMID 38165043, 2024). "In multiple myeloma cells, pomalidomide and lenalidomide induce the breakdown of Ikaros (IKZF1) and Aiolos (IKZF3), resulting in IRF4 downregulation and cell growth defects." (PMID 34764413, 2021). "In Multiple myeloma, the continuous expression of Ikaros family zinc finger protein 1 (IKZF1) and Ikaros family zinc finger protein 3 (IKZF3) is essential for the proliferation and survival of the myeloma cells." (PMID 32591583, 2020). "As an alternative approach, we employed the thalidomide derivative lenalidomide, which has been shown to induce the proteasomal degradation of IKZF3 (and IKZF1) and is used therapeutically in treating multiple myeloma." (PMID 32321757, 2020). "The immunomodulatory imide drug (IMiD) lenalidomide promotes myeloma cell death via Cereblon (CRBN)-dependent ubiquitylation and proteasome-dependent degradation of IKZF1 and IKZF3." (PMID 30760870, 2019). "For example, UBE2G1 inactivation significantly attenuated the degradation of myeloma survival factors IKZF1 and IKZF3 induced by lenalidomide and pomalidomide, hence conferring drug resistance." (PMID 30234487, 2018). "This leads to ubiquitination and proteasomal degradation of the lymphoid transcription factors Ikaros (IKZF1) and Aiolos (IKZF3), which regulate expression of other genes such as IRF4 and MYC, and are essential for the proliferation and survival of multiple myeloma cells." (PMID 35197447, 2022). "Therefore, the degradation of IKZF1 and IKZF3 decreases the expression of IRF4 and its downstream target MYC, resulting in growth inhibition of multiple myeloma cells." (PMID 34207079, 2021). "Also, the pan-PIM kinase inhibitor SGI1776 enhances lenalidomide’s anti-myeloma activity due to more effective degradation of IKZF1 and IKZF3 in MM cell lines as well as xenografts of myeloma tumors." (PMID 32987735, 2020). "Ablation of UBE2G1 significantly diminished the degradation of IKFZ1, IKZF3 and ZFP91 by LEN, POM, and CC-220, as well as CK1α degradation by LEN in OPM2, DF15 and MM1S myeloma cells." (PMID 30234487, 2018). "Interestingly, in multiple myeloma cells treatment with lenalidomide increased ubiquitination and subsequent degradation of IKZF1 and IKZF3, demonstrating that small molecules can modulate the CUL4-DDB1-DCAF complex." (PMID 26613412, 2015). "Binding lenalidomide or its analogues, thalidomide and pomalidomide, to CRBN would increase the binding of IKZF1 (Ikaros) and IKZF3 (Aiolos) proteins to the CRBN-based E3ULC, leading to increased ubiquitination and consequent degradation, which is toxic to myeloma cells." (PMID 24687382, 2014). "These molecules exert multiple direct and indirect anti-myeloma effects, primarily through binding to cereblon (CRBN), part of an E3 ubiquitin ligase complex, and promoting the ubiquitination of the IKAROS and AIOLOS family transcription factors (IKZF1 and IKZF3)." (PMID 37627065, 2023). "This issue could be overcome by either hijacking two different E3 ligases, CRBN and VHL, or a PROTAC, such as YKL-06-102, that simultaneously targets IKZF1, IKZF3, and CDK6, achieving intramolecular synergistic effects even in IMiD-insensitive multiple myeloma cells." (PMID 35197447, 2022). "Additionally, IMiDs have been found not only to have immunomodulative effects on T cells (hence the name), but also to have antiproliferative effects on multiple myeloma cell types by recruiting the transcription factors Ikaros (IKZF1) and Aiolos (IKZF3) for its degradation." (PMID 34577077, 2021). "Hence, we reasoned that resistance to IMiD drugs in myeloma could be ascribed to reduced degradation of IKZF1 and IKZF3 as a result of inactivation of other essential components of the CRL4CRBN ligase complex, for instance the E2 ubiquitin conjugation enzyme." (PMID 30234487, 2018).
multiple myeloma (continued). "Furthermore, accumulating evidence demonstrated that downregulation of IKZF3 (Aiolos) and IKZF1 (Ikaros), two members of the IKZF family, in malignant plasma cells as well as in adaptative and innate lymphocytes is key for the anti-myeloma activity of Immunomodulatory drugs (IMiDs)." (PMID 36284352, 2022).